LEP (leptin)
Diseases named in the same sentence as LEP in open-access papers (continued):
Sharing a sentence is not in itself a finding about the gene and the disease.
breast cancer (continued). "Furthermore, knowledge of the signals in the biogenesis of exosome in breast cancer (i.e., leptin signalling in obese patients) will be important for the design of new therapies." (PMID 32033341, 2020). "Leptin has been shown to up-regulate VEGFA expression in mouse mammary tumor cell lines." (PMID 32318345, 2020). "Interestingly, leptin is also involved in the regulation of VEGF in breast cancer cells via hypoxia-inducible factor 1α (HIF-1α) and NF-κB signaling promoting cancer progression." (PMID 32092997, 2020). "PKM2 was another EMT-related protein downstream of leptin in breast cancer." (PMID 33371368, 2020). "Moreover, leptin-induced breast cancer cell metastasis was due at least in part to activation of the SDF-1/CXCR4 axis." (PMID 32836215, 2020). "Notably, the leptin-induced increase in PAI-1 in breast cancer cells was significantly blocked by silencing STAT3." (PMID 33371368, 2020). "Furthermore, it was shown that leptin stimulates the secretion of interleukins (IL)-8 and -18 by TAMs, thus promoting the malignant phenotype of breast cancer cells." (PMID 32727138, 2020). "Several case-control studies associated low circulating levels of adiponectin with an increased breast cancer risk and the development of a more aggressive phenotype in post-menopausal women, regardless of BMI, leptin, and IGF-I levels." (PMID 32132979, 2020). "Leptin and the leptin receptor ObR are overexpressed in breast cancer." (PMID 33006013, 2020). "Moreover, it has been reported that ligand-activated PPARγ can also reduce tumor growth counteracting the leptin-signaling, which is well-known to sustain breast cancer progression." (PMID 33352766, 2020). "Some studies suggested high levels of serum leptin as a biomarker for breast cancer development." (PMID 32133259, 2020). "In addition, we observed that silencing STAT3 blocked the leptin-induced increase in PAI-1 in breast cancer cells." (PMID 33371368, 2020). "Furthermore, we obtained evidence that adipocytes secreted leptin to activate OBR in breast cancer cells, which phosphorylated STAT3 to promote the transcription of PAI-1 and repress the expression of miR-34a as the negative regulator of PAI-1." (PMID 33371368, 2020). "Furthermore, our findings revealed that adipocyte-derived leptin inhibited miR-34a expression in breast cancer cells by interacting with OBR." (PMID 33371368, 2020). "Leptin has been identified as a key driver in the progression of breast cancer." (PMID 32512860, 2020). "For example, EPB41, PSMA1, LEP, LECT2, and ZNF35 were associated with breast cancer." (PMID 32528533, 2020). "The SDF-1/CXCR4 axis activated by leptin also promoted bone metastasis of breast cancer." (PMID 32836215, 2020). "The increased secretion of leptin promotes metastasis by increasing the expression of epithelial–mesenchymal transformation (EMT)- and metastasis-associated genes (SERPINE1, MMP-2, and IL-6) in breast cancer cells." (PMID 32674405, 2020). "Also, leptin potentiated the proliferation, migration, and invasion of breast cancer cells via upregulating ACAT2 through the PI3K/AKT/SREBP2 signaling pathway." (PMID 33371368, 2020). "Additionally, increased expression of leptin and its receptors were demonstrated in breast cancer cell lines as well as in human breast cancer tissues." (PMID 32133259, 2020). "Indeed, rosiglitazone was revealed to prevent leptin-induced tumor growth in nude mice and to inhibit proliferation in breast cancer cells upon leptin treatment." (PMID 33352766, 2020). "It has been fully elucidated the role of leptin in breast cancer biology." (PMID 32132979, 2020). "Additionally, leptin-induced metastasis of breast cancer cells was inhibited when the SDF-1/CXCR4 axis was blocked by AMD3100." (PMID 32836215, 2020). "In addition to its direct action, other authors and we have demonstrated that leptin can modulate breast cancer biology by interacting with different signaling molecules, such as estrogen and growth factors." (PMID 32260113, 2020).
breast cancer (continued). "Src and FAK kinases play an important role in the regulation of EMT in the MCF-7 and MDA-MB-231 breast cancer cell lines, where leptin promotes MMP-2 and MMP-9 secretion, cell migration, and invasion through the activity of Src and FAK, and PI3K-activity independent." (PMID 33334030, 2020). "Based on these reports in different study models, it is suggested that leptin could be used as a potential tumor marker in the diagnosis and prognosis of lung, liver, colon, and especially breast cancer." (PMID 33334030, 2020). "Moreover, it has been proposed that higher LepR mRNA expression and leptin signaling genes had a more fatal impact on ER- subtypes compared with ER+ breast cancer." (PMID 33019728, 2020). "Notably, the activation of leptin or TGFβ signaling, which is widely observed in breast cancer patients with obesity, presents with inhibited ACC1 expression to promote the initiation of EMT." (PMID 32793598, 2020). "Our overarching hypothesis was that higher IHC expression of LEP, LEPR, ADIPOQ, ADIPOR1, and ADIPOR2 within the breast tumor microenvironment is associated with breast cancer aggressiveness, but we generally observed the opposite." (PMID 32046756, 2020). "In addition to poor prognosis and association with metastasis, NOTCH is essential for angiogenesis and growth of breast cancers, a pathway in which Leptin also plays a role." (PMID 32326381, 2020). "Additionally, leptin favors breast cancer progression by inducing cellular proliferation by binding to its receptor followed by downstream signaling through NFκB, STAT3, ERK1/ERK2, and phosphoinositide-3-kinase (PI3K) pathways." (PMID 32257945, 2020). "Indeed, hyperactive leptin signaling affects different aspects of breast cancer biology by both modulating the phenotype of neoplastic epithelial cells as well as the behavior of the different components within the TME." (PMID 32727138, 2020). "The objective of this study was to examine the expression levels of leptin and ObR in liver tissue of a transgenic breast cancer mouse model to investigate whether the roles of leptin in MT development are systemic or local." (PMID 32133259, 2020). "In addition, we investigated the effects of leptin on the metastatic capacity of breast cancer cells invitro using a transwell assays." (PMID 32836215, 2020). "Interestingly, leptin mRNA is highest for normal tissue and tumor tissue adjacent to breast cancer, but leptin is lower in primary cancer, and the lowest in metastatic cancer." (PMID 33019728, 2020). "Adipocyte-secreted leptin and IL-6 have a paracrine effect on nearby breast cancer cells." (PMID 32033341, 2020). "Additionally, leptin has been shown to be a potential prognostic marker in breast cancer, along with tumour size and lymph-node status, and an independent predictor of a poor outcome." (PMID 32512860, 2020). "Notably, leptin, in addition to its direct effects on breast cancer epithelial cells, has been demonstrated to stimulate the function of macrophages, one of the most abundant and critical immune cell types within the breast tumor microenvironment." (PMID 32260113, 2020). "Moreover, numerous studies have shown that leptin is pro-tumorigenic, with the capability to promote the proliferation, transformation, and survival of mammary epithelial and breast cancer cells." (PMID 32630445, 2020). "Furthermore, I discuss the Src-associated in mitosis of 68 kDa (Sam68), a signal transduction and activation of RNA (STAR) protein and eclectic component of signal transduction of leptin, which is strongly involved in breast cancer progression." (PMID 32033341, 2020). "NLRP3 inflammasomes mediate both suppressions of apoptosis and progression of the cell cycle by leptin-dependent ROS production in breast cancer, which is mediated via estrogen receptor alpha (ERα)/reduced nicotinamide adenine dinucleotide phosphate (NADPH) oxidase signaling." (PMID 33613533, 2020).
breast cancer (continued). "Thus, several data strongly support the involvement of leptin in common endocrine related cancer in women, especially, breast cancer." (PMID 32824322, 2020). "We found that leptin also significantly increased CXCR4 expression in breast cancer cells." (PMID 32836215, 2020). "In addition, leptin can promote recurrence and distant metastasis in breast cancer, ultimately leading to poor overall survival in late stage breast cancer patients." (PMID 32836215, 2020). "Specifically, leptin is thought to promote breast cancer through the activation of Janus kinase 2/Signal Transducers and Activators of Transcription 3 (Jak2/Stat3), mitogen-activated protein kinase (MAPK) and Phosphatidylinositol-3-kinase/Protein kinase B (PI3K-AKT)." (PMID 33019728, 2020). "The leptin-Sam68 axis appears to be essential for the growth and progression of breast cancer." (PMID 32033341, 2020). "Leptin stimulation facilitates VEGF expression in breast cancer cells via HIF-1α and NF-κB." (PMID 33123472, 2020). "Here, we investigated the expression and the intracellular distribution of KH RNA binding domain containing, signal transduction associated 1 (KHDRBS1), leptin, leptin receptor (LEPR), and adiponectin in bone metastasis from breast carcinoma and looked for correlations between the data." (PMID 33213024, 2020). "Indeed, both leptin and its receptors (ObR) are found to be overexpressed in breast carcinomas, where they correlate with higher grade, distant metastasis, and poor prognosis." (PMID 32260113, 2020). "Moreover, leptin increases the expression of cyclin D1 and cyclin-dependent kinase 2, which accelerates the cell cycle of breast cancer cells." (PMID 31500658, 2019). "The role of leptin promoting growth via ERK pathway has been demonstrated in breast cancer models." (PMID 31380268, 2019). "Thus, the effect of increased weight and BMI, as well as the role of leptin and the potential molecular mechanisms by which it contributes to breast cancer progression still remains to be elucidated." (PMID 31671408, 2019). "In contrast, another study reported that a leptin treatment may improve bioenergetic efficiency by preventing ROS formation in breast cancer cells (Blanquer‐Rossello, Santandreu, Oliver, Roca, & Valle, 2015)." (PMID 30632310, 2019). "Leptin treatment of breast cancer cells in vitro has been shown to increase SNAI2 expression." (PMID 31118047, 2019). "Leptin is a hormone secreted by adipocytes, which contributes to the progression of breast cancer." (PMID 31671408, 2019). "Thus, cAMP elevation seems to completely prevent leptin-induced migration of MDA-MB-231 breast cancer cells." (PMID 31380268, 2019). "In breast cancer cells, leptin promoted growth of breast cancer cells via autophagy activation." (PMID 31700697, 2019). "In this scenario, our results, increasing the knowledge on the signals involved in exosome biogenesis in breast cancer cells (i.e., leptin signaling), might open new avenues for therapeutic intervention in breast carcinoma, especially in obese women." (PMID 31336913, 2019). "We found that leptin promotes migration of breast cancer cells in a FAK/Src-dependent manner." (PMID 31671408, 2019). "Specifically, the activation of leptin signaling results in concurrent activation of multiple oncogenic pathways leading to an increased proliferation, epithelial-mesenchymal transition, migration and invasion of breast cancer cells." (PMID 31380268, 2019). "Furthermore, other recent study has proposed leptin to enhance the proliferation, migration and invasion of breast cancer cells via acetyl-CoA acetyltransferase 2 (ACAT2) up-regulation through the PI3K/AKT/SREBP2 signaling pathway." (PMID 31380268, 2019). "In breast cancer, leptin has been proposed to have a role at different levels." (PMID 31380268, 2019). "This suggests that a post-translational mechanism could be involved in leptin mediated Tsg101 upregulation in breast cancer cells." (PMID 31336913, 2019).
breast cancer (continued). "In addition, leptin-Notch axis seems to play a role in breast cancer development, as it has been demonstrated in some models of breast cancer cells." (PMID 31380268, 2019). "Leptin displays pleiotropic effects that include inhibition of pro-apoptotic signals in breast cancer cells, sensitization to estrogens, and modulation of the tumor microenvironment, contributing to local pro-inflammatory mechanisms and promoting mammary tumor growth." (PMID 30823902, 2019). "Leptin specifically enhances tumorigenicity of estrogen positive breast cancer cells." (PMID 31380268, 2019). "Leptin could also promote proliferation in breast cancer cells in vitro via steroid receptor coactivator (SRC)-1/STAT3 signaling pathway." (PMID 31500658, 2019). "Several leptin dependent signaling kinases, including ERK-p90-RSK and Akt, which phosphorylate GSK3β, along with the increase of MTA1 expression by leptin, regulate the function of this Wnt pathway to promote epithelial-mesenchymal transition in breast cancer cells." (PMID 31380268, 2019). "Interestingly, BITC treatment can block leptin-induced breast cancer growth by directly inhibiting leptin-mediated Stat3 activation." (PMID 31618928, 2019). "Leptin, like insulin, appears to be a growth factor for breast cancer cells." (PMID 31380268, 2019). "However, the pro-carcinogenic effect of leptin in breast cancer results not only from an enhanced activity of signaling pathways involved in the proliferation process, but also from a probable down-regulation of the apoptotic response." (PMID 31380268, 2019). "CAAs secrete more chemokine (C–C motif) ligand 2 (CCL2), chemokine (C–C motif) ligand 5 (CCL5), interleukin-1β (IL-1β), interleukin-6 (IL-6), tumor necrosis factor-alpha (TNF-α), vascular endothelial growth factor (VEGF), leptin, etc., which can promote the invasion and metastasis of breast cancer." (PMID 31500658, 2019). "The levels of serum leptin in breast cancer cases with different clinicopathological features." (PMID 30702563, 2019). "Interestingly, blocking leptin signaling by using a full leptin receptor antagonist, the peptide LDFI, completely reversed the breast CSC phenotype, further highlighting the potential advantage of targeting leptin signaling to block breast cancer malignancy." (PMID 30634494, 2019). "On the other hand, leptin and other hormones could have exerted stimulating effects on HR–negative breast cancer cell proliferation, invasion, and angiogenesis, either directly or indirectly." (PMID 31864424, 2019). "Adipokine leptin is a strong predictor of poor outcome in breast cancer." (PMID 31121868, 2019). "Therefore, we concluded that increased leptin production by obASCs promotes ER+ breast cancer through estrogen-mediated pathways." (PMID 31118047, 2019). "Furthermore, leptin and its ObR receptor are overexpressed in primary and metastatic mammary tumor tissues, suggesting an autocrine signaling mechanism developed by tumor cells." (PMID 31671408, 2019). "Indeed, several data from clinical and experimental studies strongly support the involvement of leptin in mammary tumor development and progression." (PMID 30634494, 2019). "In addition, various studies have integrated leptin and cAMP signaling pathways in breast cancer, specifically in triple negative breast cancer." (PMID 31380268, 2019). "Despite the underlying mechanisms still remain poorly understood, proteins that have been previously related to cancer as well as to insulin signaling, such as APPL1 or Sam68, seem to positively mediate leptin induced phosphorylation of the main pathways activated by this hormone in breast cancer." (PMID 31380268, 2019). "Additionally, it has been demonstrated that leptin interferes with the action of tamoxifen under beta-estradiol stimulated conditions in ER-positive breast cancer cells." (PMID 31380268, 2019). "Leptin and TGFβ1 seem to promote metastasis and stemness in breast cancer cells." (PMID 31380268, 2019).
breast cancer (continued). "Additionally, leptin is involved in the progression of breast cancer, through the activation of mitogenic, anti-apoptotic and metastatic pathways." (PMID 31671408, 2019). "Similar findings from co-culture system had been reported that the leptin produced by obese adipose stromal/stem cells could enhance proliferation in estrogen receptor positive breast cancers." (PMID 29682217, 2018). "Importantly, a decrease in adiponectin and an increase in leptin levels favor the development and progression of breast cancer." (PMID 30404206, 2018). "Therefore, our results clearly suggest that adipocyte-derived IL-6 and leptin promote the invasive phenotype of breast cancer cells via upregulation of PLOD2 both in vitro and in vivo." (PMID 30563531, 2018). "So, leptin may interfere with the efficacy of breast cancer treatments, especially anti-estrogens like Tx that targets ER." (PMID 29389973, 2018). "Furthermore, HIF-1α and NFκB were proposed as the major route in leptin-dependent VEGF-A induction in breast cancer." (PMID 29682217, 2018). "The overexpression of leptin and the ObR receptor also promotes the progression of breast cancer." (PMID 30404206, 2018). "Despite of the elevated serum level of leptin, LepR-deficient mice (db/db) failed to develop breast cancer in an oncogene-induced rodent model (MMTV-TGF-alpha mice)." (PMID 30013512, 2018). "However, the pro-tumor effects of leptin depend on its receptor LepR, which is expressed in various tumors, including breast cancer, prostate cancer, and colon cancer." (PMID 30013512, 2018). "A recent clinical study found that BMAs in breast cancer patients but not healthy controls were positively associated with serum leptin level." (PMID 30013512, 2018). "However, in our study we confirmed that IL-6 and leptin were responsible for the adipocyte-mediated upregulation of PLOD2 in breast cancer." (PMID 30563531, 2018). "However, diverse studies have shown that leptin and its receptor, ObR, are overexpressed in patients with breast cancer." (PMID 30404206, 2018). "Furthermore, breast cancer cells cocultured with adipocytes or treated with either IL-6 or leptin displayed increased PLOD2 expression and activated JAK/STAT3 and AKT signaling pathways." (PMID 30563531, 2018). "We next determined whether suppression of CCN5 by leptin is a relevant episode in leptin-mediated ER-α-positive breast cancer cell viability." (PMID 29370782, 2018). "Treatment with a murine IL-6 blocking antibody or depletion of OBR abrogated both the expression of PLOD2 and adipocyte-stimulated metastasis, indicating that PLOD2 plays an important role in mediating breast cancer metastasis via adipocyte-derived IL-6 and leptin." (PMID 30563531, 2018). "Based on the observation that adipocyte-derived IL-6 and leptin promoted PLOD2 expression in breast cancer cells, we next explored whether IL-6 and leptin activated JAK/STAT and AKT signals in vitro." (PMID 30563531, 2018). "Thus far, we have demonstrated that IL-6 and leptin are increased in adipocytes and/or adipocytes cocultured with breast cancer cells." (PMID 30563531, 2018). "In their working model, leptin stimulates receptor and ligand expression in breast cancer cells." (PMID 29915603, 2018). "We demonstrated that leptin treatment of breast cancer cells can increase TGFB1 expression." (PMID 28542577, 2017). "Previous studies have reported that levels of leptin were not only correlated with tumor size but also with tumor hormonal receptor status (ER and progesterone receptor (PR)) and were significantly higher in breast cancer patients than healthy controls." (PMID 29088874, 2017).